RNU5E-7P (RNA, U5E small nuclear 7, pseudogene)
Gene: Small nuclear RNA gene on chromosome 2 (15,864,935 to 15,865,051, forward strand). Ensembl gene ENSG00000202160.
Homologues: Orthologues: chimpanzee U5 (98% identical), macaque U5 (95% identical), dog U5 (77% identical). Paralogues in human: RNU5E-4P (81% identical), RNU5A-4P (80% identical), RNU5F-7P (80% identical), RNU5A-7P (79% identical), RNU5B-4P (78% identical), RNU5E-8P (76% identical), RNU5F-3P (76% identical), RNU5A-6P (75% identical), RNU5E-10P (74% identical), RNU5F-6P (74% identical), RNU5E-6P (74% identical), RNU5A-3P (72% identical), and 13 more.